KRAS (KRas proto-oncogene, GTPase)
Diseases named in the same sentence as KRAS in open-access papers (continued):
Sharing a sentence is not in itself a finding about the gene and the disease.
lung cancer (continued). "KRAS mutations are particularly frequent in pancreatic ductal adenocarcinoma (PDAC), colorectal (CRC), and nonsmall cell lung cancers (NSCLC)." (PMID 31847096, 2019). "We further demonstrated that this collateral sensitivity induced by drug resistance also applies to KRAS-mutant lung cancer cells that have undergone de novo intratumor heterogeneity." (PMID 31431614, 2019). "EGFR mutation, KRAS mutation, and EML4-ALK in lung cancer case were commonly annotated resistance information by OKR and QCII." (PMID 31383922, 2019). "In a recent study, we reported that pemetrexed-resistant KRAS-mutant lung cancer cells assume a mesenchymal phenotype and cross-resist MEK inhibitors." (PMID 31612108, 2019). "In accordance, in a KRAS G12D-driven mouse model of lung cancer, it was shown that Gr1+ cells not only favor tumor growth but also reduce the infiltration with T-cells, inhibiting anti-PD-1 efficacy." (PMID 31847096, 2019). "One reason is that the G12C substitution (44%), the most common subtype in KRAS-mutant lung cancer, shows more prominent engagement with MAPK signaling." (PMID 31612108, 2019). "Here we found that KRA-533-induced hyperactivation of mutant KRAS led to apoptosis and autophagic cell death in mutant KRAS lung cancer cell lines (i.e. A549, H157 and Calu-1)." (PMID 30971271, 2019). "Our results pinpoint a rational and readily translatable strategy that combines mTOR inhibitors with standard chemotherapy to treat KRAS-mutant lung cancer." (PMID 31612108, 2019). "Because HER3 facilitates EGFR-TKI resistance, our results indicate that the STAT3 blockade is a promising strategy that can be employed to eradicate EGFR-TKI-resistant lung cancers, including KRAS-mutant A549 and T790 M-mutant H1975 cells." (PMID 31619200, 2019). "Genotyping studies revealing genetic alterations in the various subtypes of lung cancer accounting for tumorigenesis led to the development of targeted therapies, namely directed to EGFR, ALK, and KRAS mutated variants." (PMID 31795465, 2019). "In KRAS mutant lung cancer cells, it was discovered that Sirt3 was significantly up-regulated in honokiol-treated KRAS mutant lung cancer cells, leading to the destabilisation of its target gene Hif-1α and induction of G1 arrest and apoptosis." (PMID 31877856, 2019). "Despite this progress, chemotherapy, radiotherapy and/or surgery remain the standard-of-care for patients with KRAS-mutant lung cancer." (PMID 31519898, 2019). "In lung cancer, the presence of KRAS amino acid substitution influences patients' prognosis and is negatively associated with patient response to targeted therapy and chemotherapy." (PMID 31612108, 2019). "For example, resistance to KRAS G12C inhibitors in pre-clinical models of lung cancer has been shown to be overcome by combined PI3K inhibition." (PMID 31878223, 2019). "Along with a more recent report finding GLUT8 as a vulnerability in KRAS/KEAP1 mutant lung cancer cell lines, these results suggest metabolic vulnerabilities exist within Redox54." (PMID 31395880, 2019). "In contrast, antagonistic interaction between this combination drugs was observed in H661 and H1650 cells which were KRAS wild-type lung cancer cells." (PMID 31484165, 2019). "Although KRAS is the most frequently mutated oncogene in NSCLC, our knowledge on the effect of KRAS mutation on the response to BEV in lung cancer is very limited." (PMID 31600989, 2019). "Naïve CD4+ cells incubated with MT KRAS TDEs isolated from human lung cancer cells were used as a control." (PMID 31635338, 2019). "A recent screen of several chemotherapy agents in a KRAS-mutant lung cancer mouse model identified two clinically approved cancer drugs that promoted anti-tumour immunity." (PMID 30626155, 2019). "This provided an explanation, at least to some extent, for the poor unresponsiveness of KRAS-mutant lung cancer patients to the first-generation TKIs targeting EGFR alone." (PMID 31612108, 2019).
lung cancer (continued). "Mining the data from The Cancer Genome Atlas (TCGA) showed that EMT is positively correlated with tumor progression and predicts poor prognosis in KRAS-mutant lung cancer." (PMID 31431614, 2019). "This is consistent with other studies reporting low TMB in EGFR, ALK, ROS1, or RET-driven lung cancers [30•], but higher in KRAS or BRAF." (PMID 31172347, 2019). "KRA-533 also displays potent efficacy against tumor growth in mutant KRAS xenografts and genetically engineered mutant KRAS driven lung cancer." (PMID 30971271, 2019). "In lung cancer, the concordance of EGFR mutation is 75.27% (79/93) and the concordance of KRAS mutations 73.77% (135/183)." (PMID 31650022, 2019). "In this study, we aimed to investigate targeting epidermal growth factor receptor (EGFR) as a therapeutic approach in KRAS-driven lung cancer cells." (PMID 30935067, 2019). "This would be a very important finding since KRAS is mutated in 80% of human PDAC, 40–50% of CRC and 30–50% of lung carcinomas and is very difficult to target." (PMID 31412666, 2019). "We recently showed in a large series of lung cancer patients that besides allowing the identification of EGFR, KRAS, and BRAF mutations, NGS identified a potential driver in 36% of patients (FGFR, ERBB2, AKT, MAP2K1, STK11...)." (PMID 29890761, 2018). "We sought to expand our understanding of the pathways responsible for intrinsic resistance to MAPK pathway inhibition in a KRAS mutant lung cancer cell line using a CRISPR knockout sensitizer screen." (PMID 29912950, 2018). "We identified clinical, demographic, and regional predictors of EGFR & KRAS testing among Medicare beneficiaries with a new diagnosis of lung cancer in 2011–2013 claims." (PMID 29554880, 2018). "Together, these data suggest that ERK activation plays a vital role in mediating the inhibitory effects of BCI treatment in KRAS or EGFR mutant lung cancer cells." (PMID 30475204, 2018). "Animal models have given clear evidence that LKB1 haploinsufficiency stimulates KRAS driven lung cancer in mice, and a single copy inactivation of LKB1 can considerably ease brain recurrence." (PMID 29868480, 2018). "Mechanistic evaluation of one gene, GATAD2B, illuminates its role as a dual activity gene, promoting both pro-tumorigenic and pro-metastatic activities in KRAS-mutant lung cancer through interaction with c-MYC and hyperactivation of the c-MYC pathway." (PMID 30013058, 2018). "In our investigation of 2011–2012 claims, we treated code 83912 in the combination with diagnosis codes for lung cancer as a proxy for EGFR/KRAS testing, but this type of analysis can only yield approximate numbers." (PMID 29554880, 2018). "Notable ORFs enriched in metastatic tissues include GNAS and MYC, which were previously shown to promote KRAS-driven lung cancer metastasis." (PMID 30013058, 2018). "Here, for the first time, we document that deltarasin produces both apoptosis and autophagy in KRAS-dependent lung cancer cells in vitro and inhibits lung tumor growth in vivo." (PMID 29440631, 2018). "This work defines that miR-30c and miR-21 are specifically activated by KRAS and play an important role in lung cancer development and chemoresistance by targeting crucial tumor suppressor genes." (PMID 29440633, 2018). "Mutual exclusiveness between KRAS and EGFR mutations led to the three classifications of lung cancer groups: KRAS mutants, EGFR mutants, and KRAS/EGFR wild type." (PMID 29504894, 2018). "miRNA-768-3p was found to be underexpressed in in vitro lung cancer cells after co-culture with astrocytes, driving to increased KRAS protein and downstream effectors ERK1/2 and BRAF, thereby boosting tumor cell viability and promoting metastasis." (PMID 29868480, 2018). "The procedure can be used to identify a broad range of mutations, including KRAS, BRAF, and EGFR mutations, in patients with colon carcinoma, breast cancer, melanoma, and lung cancer." (PMID 29728089, 2018).
lung cancer (continued). "In this study the authors perform an in vivo functional screening and identify GATAD2B as a driver of tumor growth and metastasis in KRAS-driven lung cancer." (PMID 30013058, 2018). "As above shown, the study of KRAS-mutant mouse lung cancer was of fundamental importance to try to define some vulnerabilities of these tumor cells and to define potential therapeutic approaches." (PMID 30060526, 2018). "Of interest, honokiol was also observed to induce apoptosis through increasing the expression of Bax, while decreasing the expression of Bcl-2 in KRAS-mutant lung cancer cells." (PMID 29892225, 2018). "Among those genes, functional characterization of GATAD2B illuminates its role as a potent driver of tumor growth and metastasis in KRAS-driven lung cancers." (PMID 30013058, 2018). "In mouse lung cancer models Mmp10 was shown to be induced in bronchio-alveolar stem cells transformed by oncogenic KRas mutant and to promote KRas-mediated bronchio-alveolar stem cell expansion and lung cancer formation." (PMID 30060526, 2018). "A/J strain is susceptible to lung cancer and after DEN exposure they developed lung adenocarcinomas which were positive for KRAS mutation in the 80% of the cases." (PMID 29415661, 2018). "KRAS, as a member of the RAS family, is a small GTPase that frequently mutated in a wide range of cancers including pancreatic, colorectal, and lung cancers." (PMID 30406144, 2018). "Consistent variability in growth rate, survival and drug response has been observed in KRAS mouse lung cancer models, despite the shared initiating event; therefore, it is difficult to translate the observations made in these models into clinical application." (PMID 30060526, 2018). "Since KRAS mutations are the most common oncogene mutations in lung adenocarcinomas, implicated in over 30% of all lung cancer cases, we examined the ability of deltarasin to inhibit KRAS-dependent lung cancer cell growth." (PMID 29440631, 2018). "We found that RASA1 enforced expression reduced cell proliferation and increased the response to cisplatin in KRAS mutant lung cancer cells." (PMID 29440633, 2018). "Corcoran and coworkers reported the results of a pooled shRNA-drug screen designated to identify MEK inhibitor-based targeted therapy for KRAS mutant lung cancers." (PMID 30060526, 2018). "We studied the effects of EPZ028862 in a panel of KRAS mutant lung cancer cell lines including A549, for which RNAi-based knockdown studies had previously suggested an important role for SMYD3 in proliferation." (PMID 29856759, 2018). "For example, TIMP-1 is a key downstream modulator of NF-κB-dependent tumour growth in mouse KRAS-driven lung cancer models and represents a potentially safer therapeutic target than IKKβ." (PMID 30142927, 2018). "Sensitivities of 0.005–0.1% for EGFR-T790M (own unreported data,), 0,1% and 0,5% for ALK-C1156Y and ALK-G1269A in lung cancer and 0.025% for KRAS in CRC are reached." (PMID 29568401, 2018). "We demonstrate that deltarasin inhibits the interaction of with PDEδ as well as the downstream RAF/MEK/ERK, PI3K/AKT signaling pathways in KRAS-dependent lung cancer cells." (PMID 29440631, 2018). "Certain subtypes of cancers such as ER positive, HER-2 positive breast cancer and KRAS induced lung cancer cells have been found to be particularly vulnerable to Cdk4/6 inhibition." (PMID 29789630, 2018).
lung cancer (continued). "The IC50 values of these two KRAS-dependent lung cancer cell lines were 5.29 ± 0.07 and 4.21 ± 0.72 μM, respectively." (PMID 29440631, 2018). "KRAS aberrations have a synergistic effect with LKB1 inactivation on lung cancer development and distant metastasis formation." (PMID 29868480, 2018). "In contrast, the MEK inhibitor-sensitive lung cancer cell lines are enriched with KRAS mutations, suggesting that DREBIC analysis is capturing the inherent biology of these cells as oncogenic KRAS mutant cells dependent on aberrant MEK signaling pathway." (PMID 30323222, 2018). "In mouse lung cancer models, LKB1 downregulation does not drive tumorigenesis by itself but it induces a more aggressive phenotype in KRAS-driven tumors, suggesting a role in lung cancer progression and metastasis." (PMID 29734788, 2018). "In another study, concurrent delivery of miR-34a and KRAS-siRNA using a lipid/polymer nanoparticle led to antitumor effects in a lung cancer mouse model." (PMID 29295989, 2018). "Our study also highlights that these 70 HKGs maintain low levels of variance across tumour samples when compared to accepted markers of lung cancer (e.g., KRAS, ALK, RET)." (PMID 29761043, 2018). "The brain microenvironment negatively regulates miRNA-768-3p to enhance KRAS expression that promotes the propagation of lung cancer brain metastasis." (PMID 29868480, 2018). "To identify such drivers, we use an animal model of KRAS-mutant lung adenocarcinoma to perform an in vivo functional screen of 217 genetic aberrations selected from lung cancer genomics datasets." (PMID 30013058, 2018). "To confirm this finding, we examined glutamine metabolism in mutant KRAS-driven human A549 lung cancer cells cultured in multiple environments." (PMID 28826492, 2017). "Mining gene expression data of lung cancer cell lines identified additional TSGs suppressed by KRAS signaling whose expression was restored by inhibition of miR-29b and re-expression of TET1." (PMID 29088821, 2017). "Several papers have reported relationship between FDG uptake in lung cancer and EGFR and KRAS gene mutations." (PMID 28881771, 2017). "Next, the levels of KRAS and EGFR mutations in the plasma were determined in the 52 patients (36 with EFGR L858R mutation and 16 with KRAS exon 2 mutation) with early stage lung cancer before surgery (day zero)." (PMID 28382702, 2017). "In fact, FADD has recently been shown to promote lung cancer progression in a KRAS-driven, genetically engineered mouse model." (PMID 28212753, 2017). "Efforts to pharmacologically inhibit oncogenic KRAS, however, have been largely unsuccessful and developing targeted therapies for KRAS-driven lung cancer remains a significant challenge." (PMID 29267283, 2017). "MiR-217 also inhibits cell migration and invasion of lung cancer cells by targeting KRAS and thereby enhancing lung cancer cell sensitivity to CDDP." (PMID 29383199, 2017). "In a similar comparison with Jena PME and QIAsymphony, the QIAamp kit yielded highest concentrations of mutant KRAS in plasma samples from non‐small cell lung cancer patients." (PMID 28940814, 2017). "It has a strong potential as an anticancer agent because of its ability to induce G1 arrest and apoptosis to inhibit KRAS mutant lung cancer cell growth by disrupting oncogenic KRAS-mediated RAF/MEK/ERK and RAF/PI3K/AKT signaling pathway." (PMID 28443025, 2017). "For EGFR and KRAS involved in lung cancers, striking differences in molecular alterations of these genes have been found in never and ever smokers." (PMID 28430611, 2017). "Although the KRAS mutation, which resulted in EGFR-independent ERK activation, was suggested to be a potential biomarker for predicting the efficacy of EGFR TKI in lung cancer, it was rare in HNSCC." (PMID 28134774, 2017).
lung cancer (continued). "We found that honokiol induced cytotoxicity and inhibited proliferation of KRAS mutant lung cancer cells, compared to the normal lung cells with lower cytotoxicity." (PMID 28443025, 2017). "This is consistent with the sustained durable tumour regressions seen with selumetinib plus ABT‐263 in KRAS‐mutant colorectal xenograft models and KRAS‐driven lung cancer genetically engineered mouse models." (PMID 28548464, 2017). "In the Uppsala lung cancer cohort, RANK positivity was significantly associated with the presence of KRas mutations." (PMID 29118048, 2017). "In particular, gene sets related to KRAS, EGFR, mir-let7a3 were found to be significantly associated with lung cancer survival." (PMID 28697753, 2017). "Here, we demonstrated the cytotoxic function of honokiol in lung cancer cells harboring oncogenic KRAS for the first time." (PMID 28443025, 2017). "We then isolated lung cancer cells from KRas;rank+/+ and KRas;rankfl/fl mice using RANKL induction of PGC1β as a readout; inhibition of AKT and NF-κB, but not of p38, abrogated RANK-mediated PGC1β induction." (PMID 29118048, 2017). "For example, EMT was recently reported as a key factor of chemo-resistance in lung cancer, so is the KRAS signaling in germ-cell tumors." (PMID 28404903, 2017). "In the context of the very high penetrance of KRAS mutations in pancreatic cancers, targeting metabolic enzymes was effective in treating KRAS-mutant tumours in pre-clinical lung cancer models." (PMID 28163917, 2017). "MEK inhibition in combination with chemotherapy has shown beneficial effects in KRAS mutant lung cancer and biliary tract cancer." (PMID 29296181, 2017). "Till today, we have only limited data concerning the evaluation of the most frequent mutations in EGFR, KRAS, BRAF genes in CNS metastases of lung cancer (especially AC type)." (PMID 28097440, 2017). "Our prior work found that USP18 affected stability of cyclin D1 and KRAS, proteins that are overexpressed or constitutively activated in lung cancer cases [19 and LM Mustachio personal communication]." (PMID 27980214, 2017). "We have found that KEAP1 loss modulates sensitivity to inhibition of EGFR, ALK, BRAF, or MEK in lung cancer cell lines with EGFR, ALK, BRAF, KRAS, or NRAS mutations." (PMID 28145866, 2017). "The result from laboratory transgenic mice model study has demonstrated that HK2 is required for tumor initiation and maintenance in KRas-driven lung cancer." (PMID 28427230, 2017). "Recently, the combination of rapamycin with lipophilic bisphosphonates has been shown to be highly therapeutic in KRAS-mutant lung cancers both in vitro and in vivo." (PMID 28208579, 2017). "Applying this treatment regimen to the KRAS G12D lung cancer cell lines likewise resulted in acute sensitivity to MEK/PI3K/HDAC inhibitor combination." (PMID 28152508, 2017). "In the present study, we observed induction of apoptosis in honokiol-treated KRAS mutant lung cancer cells, which was supported by an increased amount of cleaved PARP and pro-apoptotic proteins Bax, with a reduction of anti-apoptotic Bcl-2 protein." (PMID 28443025, 2017). "Based on this preclinical evidence, several clinical trials have tested or are testing the efficacy of MEK inhibitors in KRAS-mutant lung cancer patients and colorectal cancer." (PMID 29296181, 2017).